MEF2C (myocyte enhancer factor 2C)
Diseases named in the same sentence as MEF2C in open-access papers (continued):
Sharing a sentence is not in itself a finding about the gene and the disease.
schizophrenia (24 papers, 2016 to 2025). A major psychotic disorder characterized by abnormalities in the perception or expression of reality. "Genome-wide association studies (GWAS) have identified common variants in the MEF2C gene that are associated with schizophrenia (SCZ) intelligence (IQ) and educational attainment (EA)." (PMID 39259737, 2024). "Here we take an individual gene associated with schizophrenia and cognitive function called MEF2C, which on its own is a very important regulator of brain development." (PMID 39259737, 2024). "A genome-wide association study demonstrated that among 349 genes in 108 schizophrenia-associated loci, the MEF2C gene was one of only few to be overexpressed preferentially during the middle-to-late stage of cortical development." (PMID 36834528, 2023). "The data derived by the Schizophrenia Working Group of the Psychiatric Genomics from the set of 108 schizophrenia risk haplotypes identified at least two motifs related to the potential MEF2C target sites." (PMID 36834528, 2023). "Increasing expressions of MEF2C in the prefrontal lobe of cognitive impaired mice models with schizophrenia by using adeno-associated virus vectors significantly improved cognitive abilities." (PMID 34991657, 2022). "There are MEF2C target sites in the heritable risk factors for schizophrenia, which associate MEF2C with this disease." (PMID 34991657, 2022). "Mef2c is also linked to Rett syndrome or severe Rett-like encephalopathies as well as schizophrenia and autism spectrum disorders characterized by dysmorphic features and cerebral malformations." (PMID 35408913, 2022). "In this study, we demonstrated that prenatal exposure to BP-3 caused substantial increase in Mef2c, Grin2a, and Chrna4 which corresponds to upregulation of these genes in brains of schizophrenia patients as detected in post-mortem." (PMID 30402708, 2019). "Recently, 108 genomic loci were identified by SNP meta-analysis as conferring significant risk for SCZ, and MEF2C was identified as a candidate risk gene (Schizophrenia Working Group of the Psychiatric Genomics Consortium, 2014)." (PMID 27779093, 2016). "Notably, MEF2C is also implicated in schizophrenia through GWAS46 and encodes a transcriptional regulator of activity-dependent immediate early genes such as JUN and FOS47." (PMID 35760976, 2022). "Therefore, MEF2C transcription factors are promising targets for treatment of schizophrenia-associated cognitive impairment." (PMID 34991657, 2022). "Interestingly, multiple MEF2C motifs were also found within schizophrenia risk loci, while Mef2c overexpression in cortical neurons of adult mice improved cognitive performance after psychotogenic drug treatment." (PMID 34299232, 2021). "Genetic studies have identified MEF2C as a gene that influences cognition and risk for neuropsychiatric disorders, including autism spectrum disorder (ASD) and schizophrenia (SCZ)." (PMID 39259737, 2024). "Prior studies show that both of these genes show increased expression in schizophrenia patients’ brains compared to controls; Mef2c in the prefrontal cortex and Calb2 in the dentate gyrus." (PMID 35941129, 2022). "Schizophrenia-associated genes identified from snRNA-seq in postmortem brains were found to be highly regulated by a few TFs (SATB2, SOX5, MEF2C, and TCF4), also overlapping GWAS risk loci." (PMID 34299232, 2021). "Therefore, MEF2C should be considered as a promising therapeutic target for the treatment of schizophrenia-related cognitive deficits." (PMID 36834528, 2023). "Similarly to MEF2C, the area containing the gene for EMX1 is itself a candidate schizophrenia risk locus." (PMID 36070311, 2022). "Several molecular pathways have been implicated in abnormal synaptic pruning in schizophrenia, including complement C4A overexpression, kynurenine pathway imbalance (KYNA/QUIN), and dysregulation of microglial and transcriptional modulators such as MEF2C and TCF4." (PMID 41169352, 2025).
schizophrenia (continued). "Down-regulation of MEF2C in cell culture models showed hypermethylation of H3K4 in affected nucleosomes, similar to the changes observed in prefrontal lobes of schizophrenia." (PMID 34991657, 2022).
autism spectrum disorder (15 papers, 2011 to 2025). A spectrum of developmental disorders that includes autism, and Asperger syndrome. "Human MEF2C haploinsufficiency results in Autism Spectrum Disorder (ASD), but it is unclear if the same is true in mice." (PMID 29133852, 2017). "As MEF2C participates in activity-dependent synaptic elimination, any dysfunctions in MEF2C may restrict this process leading to autism spectrum disorders (ASD) syndrome." (PMID 36834528, 2023). "Similarly, conditional deletion of MEF2C, but not MEF2A and MEF2D, is linked with altered memory formation and synaptic plasticity in the hippocampus, and MEF2C-related aberrations have been implicated in the development of autism-spectrum disorders (ASDs)." (PMID 38796067, 2024). "Moreover, we have recently shown that conditional knockout of Mef2c in mice during very early brain development – at the NPC stage – impairs neurogenesis, migration, and synaptogenesis in vivo, resulting in a behavioral phenotype resembling Autism-spectrum disorders." (PMID 21901155, 2011).
Cognitive impairment (14 papers, 2016 to 2025). Abnormal cognition is characterized by deficits in thinking, reasoning, or remembering. "Myocyte‐specific enhancer factor 2C (MEF2C), a transcription factor expressed in various brain cell types, has been implicated in cognitive disorders." (PMID 39350345, 2024). "High expression of MEF2C in brain regions traditionally linked with learning and memory is another presumption for its contribution to cognitive impairments in AD." (PMID 36834528, 2023). "The association between MEF2C and cognitive impairment coincides with the role of MEF2C in AD and ASD." (PMID 34991657, 2022). "All patients with MEF2C gene mutation presented with cognitive impairment, gross motor delay, speech disorder and autistic features." (PMID 30376817, 2018). "Moreover, Mutations or deletions of MEF2C cause a rare genetic disorder, MEF2C haploinsufficiency syndrome, which is characterized by hypotonia, seizures, and cognitive impairments." (PMID 39920775, 2025). "Thus, pharmacological inhibition of cGAS protected against synapse loss and cognitive deficits in the P301S tauopathy model, likely via enhancing the MEF2C transcriptional network and associated cognitive resilience." (PMID 37095396, 2023). "By contrast, inhibition of cGAS enhanced the MEF2C transcriptional network and rescued cognitive deficits despite similar tau pathology, enhancing cognitive resilience." (PMID 37095396, 2023). "Type I interferon (IFN-I) accumulation down-regulates the MEF2C in microglia, leading to excess microglia responses under pro-inflammatory environments of AD or aging brains, and aggravates cognitive impairment and disease pathology." (PMID 34991657, 2022). "Taken together, these results show that chronic treatment of Mef2c-het mice with NitroSynapsin significantly improved cognitive deficits, repetitive behavior, impaired social interactions, and possibly altered anxiety." (PMID 29133852, 2017). "Similar to human patients showing cognitive impairment, Mef2c-het mice performed poorly in the Barnes maze, a test that measures spatial learning and memory function." (PMID 29133852, 2017). "Therefore, expression levels of MEF2C mRNA in leukocytes may not only be a biomarker for AD diagnosis, but be a potential biomarker for early detection of cognitive decline, such as mild cognitive impairment (MCI)." (PMID 34991657, 2022).
hepatocellular carcinoma (12 papers, 2015 to 2023). A malignant tumor that arises from hepatocytes. "In fact, in hepatocellular carcinoma, cytoplasmatic MEF2C inhibited malignant cell proliferation, whereas nuclear MEF2C was associated with increased malignancy through angiogenesis and tumor invasion." (PMID 37762600, 2023). "Altered MEF2C regulation has been implicated as driver of cancer development, and it acts as an oncogene for immature T-cell acute lymphoblastic leukaemia, myeloid leukaemia, hepatocellular carcinoma, and pancreatic ductal adenocarcinoma." (PMID 37146029, 2023). "In the nucleus of hepatocellular carcinoma, MEF2C promoted the invasion and angiogenesis of hepatocellular carcinoma cells, while cytoplasmic MEF2C isolated β-catenin in the cytoplasm and reduced the ability of β-catenin to promote cell proliferation." (PMID 34991657, 2022). "On the other hand, in hepatocellular carcinoma, MEF2C was overexpressed, mediating VEGF induction of vasculogenic mimicry, migration, and invasion, and presenting both oncogenic and tumor-suppressive properties." (PMID 33673112, 2021). "Overexpression of MEF2C can regulate hepatocellular carcinoma progression through endothelial growth factor and wnt/beta-catenin signaling pathway." (PMID 29137293, 2017). "Similarly, in hepatocellular carcinoma, MEF2C-silenced cells appeared to counteract the migratory effect caused by vascular endothelial growth factor (VEGF) overexpression, by maintaining the percentage of the wound area." (PMID 37762600, 2023). "Myocyte enhancer factor 2C was overexpressed in hepatocellular carcinoma." (PMID 34733853, 2021). "MEF2C was associated with VEGF and Wnt/β-catenin signaling pathways in hepatocellular carcinoma." (PMID 33673112, 2021). "Moreover, Mef2c played double-edged roles in hepatocellular carcinoma, which could mediate VEGF-induced malignancy enhancement and also inhibit hepatoma carcinoma cells proliferation through blockade of Wnt/β-catenin signaling." (PMID 29383134, 2017). "In hepatocellular carcinoma cells, VEGF-induced VM is also reported to involve myocyte enhancer factor 2C (MEF2C) together with β-catenin via the p38 MAPK and PKC signaling pathways." (PMID 27608016, 2016). "In hepatocellular carcinoma cells, VEGF-induced vasculogenic mimicry is also reported to involve Myocyte Enhancer Factor 2C (MEF2C) together with β-catenin via the p38 MAPK and PKC signaling pathways." (PMID 26584646, 2015). "MEF2C has recently been proposed as a new oncogene, promoting metastasis in pancreatic adenocarcinoma by inducing MMP10 transcription and mediating VEGF induction of vasculogenic mimicry, migration, and invasion in hepatocellular carcinoma." (PMID 31930767, 2020).
depression (11 papers, 2017 to 2025). "We aim to conduct further investigations to comprehensively explore the role of TCF4B and MEF2C in CRS-associated depression." (PMID 38827438, 2024). "TCF4 and MEF2C emerged as potentially crucial for CRS-associated depression development." (PMID 38827438, 2024). "SNPs in the locus encoding MEF2C are the top signal in meta-analyses for major depression." (PMID 32012148, 2020). "Some DEGs linked to depression and neuroinflammation (BDNF, CCL2 (Curzytek and Leśkiewicz, 2021), STC1, MEF2C) were also downregulated in Cit200 over time." (PMID 39055655, 2024). "In our Australian sample of 3664 unrelated major depression cases and 7113 unrelated controls, SNP rs10514299 between TMEM161B and MEF2C and SNP rs11209948 near NEGR1 were nominally associated with major depression (P⩽0.05)." (PMID 28509901, 2017). "In addition, the DeepWAS identified an SNP on the transcription factor binding site of MEF2C on chromosome 8 as a regulator for depression." (PMID 39028994, 2024). "TCF4 and MEF2C are potential therapeutic targets for CRS with depression." (PMID 38827438, 2024).
glioma (11 papers, 2017 to 2025). A benign or malignant brain and spinal cord tumor that arises from glial cells (astrocytes, oligodendrocytes, ependymal cells). "From the up-regulated circRNAs in the stage BL (0 months), circVCAN positively regulated MEF2C-JAGGED1 axis via sponging miR-488-3p to promote proliferation of glioma cells." (PMID 41327336, 2025). "In accordance with our data, MEF2C’s silencing was shown to promote a reduction in glioma cells’ migration and proliferation, in addition to an increase in cell apoptosis." (PMID 37762600, 2023). "PVT1 also upregulated miR-190a-5p and miR-488-3p, resulting in inhibited expression of myocyte enhancer factor 2C (MEF2C), an oncogenic factor in glioma." (PMID 34322395, 2021). "For instance, PVT1/miR-190a-5p-miR-488-3p/MEF2C signaling was indicated to affect the development of human glioma." (PMID 33185692, 2020). "miR-190-5p inhibits cell proliferation in glioma by inhibiting the MEF2C-JAGGED1-Notch signaling axis." (PMID 31624470, 2019). "Knockdown of this lncRNA suppresses malignant behaviors in glioma through the binding and upregulation of miR-190a-5p and miR-488-3p, which target and inhibit myocyte enhancer factor 2C (MEF2C), which is also transcriptionally regulated by the oncogene jagged 1 (JAG1)." (PMID 33980320, 2021). "Furthermore, miR-190-5p promotes apoptosis in the glioma cell lines U251 and U87 by targeting MEF2C." (PMID 31624470, 2019). "Some intriguing aspects of the core gene set identified in this study include the well-studied glioma-related genes ANGPT2, CD44, SPP1, STAT3, PDGRFA, and TOP2A (all up-regulated), and BRSK1, DKK3, FGFR2, MAPK9, MEF2C, and PTEN (all down-regulated)." (PMID 29352201, 2018). "Still no reports have been published about effects of MEF2C on gliomas." (PMID 29137410, 2017). "To understand whether the MEF2C expression pattern was specific to BCBM, we analyzed 10 brain tissue samples derived from glioma patients as non-BCBM controls." (PMID 33673112, 2021).
heart failure (11 papers, 2011 to 2026). Inability of the heart to pump blood at an adequate rate to meet tissue metabolic requirements. "Recently, splicing dysregulation in MEF2C towards another repressor variant, MEF2Cγ, had also been shown to contributes to the pathogenesis of heart failure by promoting cardiomyocyte dropout." (PMID 39045460, 2024). "The MEF2C isoform is reported to induce cell cycle reentry and the development of heart failure in cardiomyocytes." (PMID 36978617, 2023). "MEF2c belongs to the MEF2 transcription factor family, which is expressed in a variety of cells and associated with neurodevelopmental disease, heart failure, and vascular inflammation." (PMID 36014574, 2022). "In the present study, our results showed that the binding of total AcH3, as well as the subtype AcH3K9, was reduced, and that the binding of active transcription factors GATA4 and Mef2c was decreased near the Atp2a2 promoter region after heart failure." (PMID 30286210, 2018). "Notably, GATA4 and MEF2C show significant increases, whereas Nkx2.5 shows a decrease compared to normal groups during heart failure progression." (PMID 42021955, 2026). "Furthermore, the administration of Mef2c-primed SVF or augmented CM-fated round cells in an animal model of heart failure is needed to investigate their safety (arrhythmogenicity) and efficacy (engraftment and improving ventricular function)." (PMID 33452355, 2021). "Therefore, our results indicate that primed SVF cells transduced with Mef2c have therapeutic potential in heart failure." (PMID 33452355, 2021). "Despite its global impact on cardiac mRNA splicing, the RBFOX1-mediated isoform switch (α1 versus α2) of MEF2 genes (MEF2A, MEF2C and MEF2D) appears to be a crucial regulatory circuit contributing to the development of heart failure." (PMID 39045460, 2024). "Of the transcription factors known or predicted to regulate HCN4 (AP1, Isl1, Mef2c, Nkx2.5, NRSF, Tbx3 and Tbx18), two (Nkx2.5 and Tbx3) did not change in the sinus node in heart failure." (PMID 32647133, 2020). "In the heart failure mice, qPCR showed no significant change in Bmp2, Bmp4, Nkx2.5, Shox2 and Tbx3 in the sinus node, but there was a significant downregulation of Tbx18 and Isl1 and upregulation of AP1, Mef2c and NRSF mRNA." (PMID 32647133, 2020).
acute myeloid leukemia (10 papers, 2015 to 2025). Acute myeloid leukemia (AML) is a group of neoplasms arising from precursor cells committed to the myeloid cell-line differentiation. "Transcription factor MEF2C (Myocyte Enhancer Factor-2 C) regulates B- and T-cell development, has an oncogenic function in acute myeloid leukemia and its upregulation is directly associated with CRC progression." (PMID 36177008, 2022). "For instance, expression of MYOD1 can predict patient survival in lung cancer patients and high expression of MEF2C is associated with poor outcome in acute myeloid leukemia (AML) patients." (PMID 27874835, 2016). "LKB1-SIK signaling also maintains the activity of the oncogenic transcription factor MEF2C (myocyte-specific enhancer factor 2C) in acute myeloid leukemia linking LKB1-SIK activity to cancer." (PMID 39735555, 2025). "Integrated MEF2C and ectopic MEF2C expression are found in 20% of patients with acute myeloid leukemia (AML)." (PMID 38907739, 2024). "Recent studies have also shown that MEF2C plays an important role in myocilin mediating cancer-induced muscle wasting and cachexia in cancer patients and regulates chemotherapeutic resistance and the disease progression of acute myeloid leukemia." (PMID 36661663, 2022). "It would also be interesting to analyze whether MEF2C is phosphorylated as reported in acute myeloid leukemia where phosphorylation appeared to induce apoptosis resistance and its inhibition reverted chemotherapy resistance." (PMID 31930767, 2020). "Interestingly, overexpression of MEF2C was also observed in pretreatment bone marrow specimens from acute myeloid leukemia patients, which was correlated with MEF2C protein expression, suggesting a contribution to the aggressive nature of at least some subtypes of the disease." (PMID 31930767, 2020). "Mef2c plays oncogenic role in ALL, Acute Myeloid Leukemia (AML), colon adenocarcinoma, Diffuse Large B Cell Lymphoma (DLBCL), and T-cell lymphomas." (PMID 38110859, 2023). "In human acute myeloid leukemia (AML) cell line models, 1,25-dihydroxyvitamin D3 induces monocytic differentiation and CD14 expression, an effect that is mediated through activation of MEF2C signaling via regulation of CCAAT-/enhancer-binding protein alpha (CEBPA)." (PMID 26487643, 2015).
Rett syndrome (9 papers, 2019 to 2025). A severe neurodevelopmental disorder affecting the central nervous system. "MEF2C knockout mice displayed a spectrum of behavioral phenotypes that were observed in a Rett syndrome (RTT) animal model." (PMID 36834528, 2023). "Other hub genes (GABBR2, GRM7, MEF2C, SCN2A, KMT2C, and DAGLA) dysfunction have been reported to contribute to ASD and other psychiatric disorders such as Attention-Deficit Hyperactivity Disorder (ADHD), Huntington’s disease, and Rett-syndrome." (PMID 31649562, 2019).